GBP2 (guanylate binding protein 2)
Diseases named in the same sentence as GBP2 in open-access papers (continued):
Sharing a sentence is not in itself a finding about the gene and the disease.
colorectal cancer (19 papers, 2021 to 2025). A primary or metastatic malignant neoplasm that affects the colon or rectum. "On the other hand, low expression of GBP2 in patients with microsatellite stable colorectal cancer was associated with poor prognosis and increased metastasis." (PMID 38169731, 2023). "They found that low expression of GBP2 was associated with weakened immune responses and poor prognosis of colorectal cancer patients, which suggested that GBP2 could serve as a potential immunotherapy target for colorectal cancer." (PMID 37784054, 2023). "Mechanistically, GBP2 potentiates the cytotoxic effects of paclitaxel in both sensitive and resistant colorectal cancer models by inhibiting Wnt signaling." (PMID 41181145, 2025). "In colorectal cancer, GBP2 suppresses Wnt signaling, heightening sensitivity to paclitaxel and boosting survival rates, offering a therapeutic advantage for patients facing drug-resistant tumors by inhibiting beta-catenin-driven growth." (PMID 40564939, 2025). "It was reported that transfection of GBP2 in colorectal cancer (CRC) cells inhibited their growth and increased their sensitivity to paclitaxel in a paclitaxel-resistant CRC, impairing Wnt signaling." (PMID 35631574, 2022). "Recent studies have revealed the role of GBPs in carcinogenesis and have found that GBP2 inhibits the growth of colorectal cancer cells by interfering with WNT signal transduction." (PMID 34026364, 2021). "In cancer, the Gbp family members are among the IFNγ-dependent genes most highly induced in cancer patients, and increased tissue expression of human GBP2 in several cancer types including colorectal cancer is correlated with favorable prognostic outcomes." (PMID 34912335, 2021). "Increasing GBP2 expression enhances anti-PD-1 response and inhibits colorectal cancer growth." (PMID 41181145, 2025). "In colorectal cancer, upregulating GBP2 could enhance the response to paclitaxel, offering a promising combinatory approach." (PMID 40564939, 2025). "GBP2’s paclitaxel sensitization in colorectal cancer suggests its upregulation could guide adjuvant therapy, monitored via drug sensitivity screens, tumor biopsies, or circulating tumor DNA analysis, optimizing therapeutic outcomes." (PMID 40564939, 2025). "Why do GBP1 and GBP2 exhibit opposing roles across cancers—e.g., tumor suppression in colorectal cancer versus oncogenicity in glioblastoma—and can machine learning, multi-omics analysis, or systems biology predict these patterns from genomic, proteomic, or transcriptomic data." (PMID 40564939, 2025). "However, the expression of GBP2 was decreased in colorectal cancer, which gave rise to poor prognosis and metastasis." (PMID 37622120, 2023). "Given that GBP2 could mediate STAT1 signaling in both colorectal cancer and renal cell carcinoma, we supposed that GBP2-STAT1 axis might be critical for regulating the tumor immune status in a variety of malignancies." (PMID 37784054, 2023). "However, when it comes to colorectal cancer, GBP2 was proven to inhibit the growth of cancer cells by interfering with Wnt signal transduction." (PMID 35356208, 2022). "In addition, GBP2 exhibits immunomodulatory properties; studies suggest it promotes M1 macrophage polarization in other disease models, positioning it as a potential immunotherapy target in colorectal cancer." (PMID 41595468, 2025). "For this reason, we screened 7 m6A-related genes (IL12RB1, FASLG, CXCL13, GBP2, CXCL10, CXCR6, and CIITA) through WGCNA and LASSO regression in this study and established an m6A-GPI in colorectal cancer." (PMID 37427112, 2023). "similarly observed a positive correlation between GBP2 and CD8+ T cell infiltration in colorectal cancer." (PMID 38169731, 2023). "In paclitaxel -resistant colorectal cancer cell lines, both mRNA and protein levels of GBP2 were substantially downregulated compared to their non-resistant counterparts." (PMID 41181145, 2025).
colorectal cancer (continued). "Guanylate binding protein 2 (GBP2), a member of the GTPase family, is crucial to host immunity against pathogens and has been demonstrated as a potential immunotherapeutic target for multiple “cold” tumor, such as proficient-mismatch-repair or microsatellite stability (pMMR/MSS) colorectal cancer." (PMID 36818162, 2023).
viral infection (13 papers, 2011 to 2025). "GBP2 has been associated with immune surveillance, immunotherapy response, immune regulation, and defense against viral infections in the tumor microenvironment." (PMID 41181145, 2025). "Whether the pathology of pancreatic cancer with high expression of GBP2 is also associated with viral infection is a question worthy of consideration and further exploration." (PMID 34026364, 2021). "GBP2 plays a major role in cell-autonomous innate immunity against bacterial, parasitic, and viral infections." (PMID 41181145, 2025). "Whether the pathology of cancers with high GBP2 expression involves viral infection merits further investigation." (PMID 41181145, 2025). "Given that many malignancies—such as liver cancer with HBV, nasopharyngeal cancer with EBV, and cervical cancer with HPV—are associated with viral infections, and considering that various viruses induce IFN production upon host invasion, GBP2 likely plays a role in host defense." (PMID 41181145, 2025). "A greater number of genes are upregulated in DCs after MRV infection, many of which are involved in the innate immune response (i.e. Ifit1, Ifit3, Mx1, Gbp2, Oasl1, Isg15, Ccr1, Ifitm2, Oaxl2, Casp1, Casp4) that would be predicted in response to a viral infection." (PMID 38895117, 2024). "Notably, the inhibition of furin by GBP2 may have implications beyond viral infection, as several bacterial toxins, such as anthrax toxin protective antigen and diphtheria toxin, also depend on furin-mediated activation." (PMID 41181145, 2025). "GBP2 may also influence cancer progression through immune regulation against viral infections." (PMID 41181145, 2025). "Thus, during an innate immune response to viral infection where multiple ISGs including GBP2/5 and IFITM1/2/3 are induced, we might expect to see stronger inhibitory effects." (PMID 36693093, 2023). "Here, we report that GBP2 and GBP5 inhibit the cleavage of SARS-CoV-2 spike and reduce viral infection." (PMID 36693093, 2023). "GBP2 belongs to the GTPase family and is significantly elevated after IFN-γ stimulation, which plays a vital role in host immunity against viral infection." (PMID 37622120, 2023). "Additionally, upregulated expression of antiviral genes such as GBP1, GBP2 and CCL2 was also observed, which is closely related to the inflammatory response elicited by viral infection." (PMID 39872814, 2024). "Similar to GBP2/5, MARCH8, and α-SNAP blocking role on viral infection by targeting furin, it is rational to deduce that PAR1 probably restricts infection of a broad spectrum of enveloped viruses, other than hMPV and HIV-1, whose envelope glycoproteins depend on furin cleavage." (PMID 36591809, 2023). "GBP2/5 and α-SNAP were IFN-inducible, while MARCH8 was not sensitive and showed highly endogenous expressions, indicating a solid intrinsic immunity defense against virus infection." (PMID 36591809, 2023).
glioblastoma (11 papers, 2021 to 2025). The most malignant astrocytic tumor (WHO grade IV). "GBP2 drives glioblastoma invasion via the Stat3/fibronectin pathway, linking immune signaling to extracellular matrix remodeling and physical tumor spread, facilitated by its homodimerization and cytoskeletal interactions." (PMID 40564939, 2025). "In contrast, in renal carcinoma, pancreatic adenocarcinoma, and glioblastoma, GBP2 overexpression promotes malignancy, often by facilitating immune evasion or Stat3-driven invasion, leading to a poorer prognosis." (PMID 40564939, 2025). "In glioblastoma multiforme, GBP2 overexpression significantly promotes cell migration and invasion in vitro, whereas its silencing produces the opposite effect." (PMID 41181145, 2025). "GBP2 was found to be highly expressed in several tumors including gliomas (glioblastoma multiforme and low-grade gliomas)." (PMID 36186425, 2022). "GBP-2 also promotes a better prognosis in breast and colon cancer, but promotes glioblastoma progression." (PMID 35681772, 2022). "These consistent results suggest that glioblastoma has higher GBP2 protein levels than normal tissue at both RNA and protein level." (PMID 36186425, 2022). "Likewise, highly expressed GBP2 contributed to the invasion of glioblastoma multiforme through Stat3/FN1 signaling pathway." (PMID 37622120, 2023). "Recent studies have explored the role of GBP2 on carcinogenesis and found that GBP2 could enhance the invasive ability of glioblastoma via the GBP2/Stat3/FN1 signal cascade." (PMID 35356208, 2022). "GBP2 has been reported to increase glioblastoma invasiveness through the Stat3/fibronectin pathway." (PMID 36186425, 2022). "GBP2 promotes glioblastoma invasiveness through the Stat3-mediated immune pathway." (PMID 36186425, 2022). "Furthermore, GBP2 is highly upregulated in human glioblastoma and enhances the invasive ability of glioblastoma via the GBP-2/Stat3/FN1 signal cascade." (PMID 34026364, 2021). "GBP2 and GBP5 are interferon-inducible guanylate-binding proteins, acting in innate immunity and exerting a tumor-sustaining function in glioblastoma." (PMID 40498028, 2025). "According to the literature, among the genes whose expressions change after treatment and have an LTR12C element at the TSS site, only IRGM, GBP2, GBP5, and TP63 are known to play a meaningful role in glioblastoma." (PMID 40498028, 2025).
melanoma (10 papers, 2020 to 2026). A malignant, usually aggressive tumor composed of atypical, neoplastic melanocytes. "To reveal the underlying mechanism of GBP2 in melanoma progression, we performed GSEA on sequencing data of TCGA-SKCM." (PMID 35937997, 2022). "Beyond paclitaxel-response, GBP2 has also been identified as a potential target of quercetin in melanoma." (PMID 41181145, 2025). "In murine melanoma B16-F1 cells, quercetin treatment upregulates GBP2 expression, which correlates favorably with prognostic outcomes." (PMID 41181145, 2025). "Herein, there was a favorable response in melanoma patients with higher GBP2 expression than those with low GBP2 expression." (PMID 40226609, 2025). "The multivariate COX regression analysis suggested that GBP2 is an independent prognostic factor in melanoma, along with the AJCC T stage (p < 0.001) and N stage (p < 0.001)." (PMID 35937997, 2022). "By comparing our GBP2 expression profiles with a published melanoma immunotherapy dataset, the results showed that high GBP2 group were highly similar to the PD-1-response group in the six cohorts." (PMID 35383115, 2022). "Functional studies suggest that GBP2 may restrain melanoma progression by modulating mitochondrial fission and inhibiting invasive behaviors." (PMID 41181145, 2025). "The prognostic significance of GBP2 and APOBEC3G in melanoma has also been backed up by other research investigations." (PMID 36211436, 2022). "We successfully separated the TCGA-melanoma samples into two subtypes on the basis of the expression of the ICD-related genes and developed a prognostic ICDRS involving 3 genes (i.e., GBP2, THBS4, and APOBEC3G) based on the DEGs between the two subtypes." (PMID 36211436, 2022). "Among them we identify BIRC3, SLIT2, GBP2, and AFAP1 to be involved in the acquisition of BRAFi resistance in melanoma cell lines." (PMID 32708687, 2020). "In this study, we found six mitochondria-related genes, BTG2, CP, LRIG1, CYP1A1, GBP2, and MBNL1, which might be targets of quercetin in melanoma and play crucial roles in melanoma." (PMID 37869567, 2023). "Combining the results of RNA-seq, molecular docking, and bioinformatics analysis, we found six mitochondria-related genes, BTG2, CP, LRIG1, CYP1A1, GBP2, and MBNL1, which might be targets of quercetin in melanoma and provide an available targeting therapy strategy for melanoma." (PMID 37869567, 2023). "However, four genes, i.e., HPDL, GRIPAP1, GBP2, and TRIM34, have been reported to exhibit prognostic significance with respect to melanoma for the first time, while HAPLN3, CCL8, FCGR2A, and IFITM1 have been reported to relate with the initiation and immune microenvironment of cutaneous melanoma." (PMID 36818162, 2023). "However, the function of GBP2 in melanoma has not been revealed." (PMID 35937997, 2022).
cutaneous melanoma (6 papers, 2021 to 2025). A primary melanoma arising from atypical melanocytes in the skin. "It is reported that GBP2 exerted anti-tumour effects by inhibiting the Wnt/β-catenin pathway in skin cutaneous melanoma (SKCM) and showed an association with poor prognosis in SKCM when its expression decreased." (PMID 36211436, 2022). "GBP2 has also been implicated in the prognosis of pancreatic cancer, cutaneous melanoma, and is involved in cutaneous melanoma progression through the Wnt/beta-catenin pathway." (PMID 36186425, 2022). "In skin cutaneous melanoma, GBP2 dampens development and metastasis by inhibiting Wnt/β-catenin signaling, suggesting its utility as both a prognostic biomarker and anti-metastatic target." (PMID 41181145, 2025). "The upregulation of GBP2 gene expression is positively correlated with outcomes in cutaneous melanoma." (PMID 34708131, 2021).
glioma (6 papers, 2021 to 2025). A benign or malignant brain and spinal cord tumor that arises from glial cells (astrocytes, oligodendrocytes, ependymal cells). "Logistic regression also illustrated an association between GBP2 and glioma clinical characteristics." (PMID 36186425, 2022). "Further analysis of glioma subgroup revealed that high GBP2 expression was significantly associated with high-grade gliomas patients." (PMID 36186425, 2022). "The results showed that GBP2 had good diagnostic ability in glioma, WHO grade (G2 vs. G4, G3 vs. G4), 1p/19q codeletion." (PMID 36186425, 2022). "Kaplan-Meier curves revealed that high GBP2 expression was linked with worse survival of glioma patients, and multivariate Cox regression analysis indicated that high GBP2 expression was an independent prognostic factor for glioma." (PMID 36186425, 2022). "The glioma datasets from the CGGA database also verified that high GBP2 expression was associated with poor prognosis in glioma patients." (PMID 36186425, 2022). "Our results first decipher immune-related characteristics and noncoding regulators of GBP2 in glioma, which may provide insights into associated immunotherapies and prognostic predictor." (PMID 36186425, 2022). "We therefore investigated the effect of GBP2 on glioma prognosis and explored the immune-related mechanisms, hoping to deepen the understanding of potential immunotherapeutic target in glioma." (PMID 36186425, 2022). "Altogether, these results indicate that GBP2 expression is likely to affect immune-related pathways in patients with glioma." (PMID 36186425, 2022). "The analysis demonstrated that the expression of GBP2 has an important impact on clinicopathological features in glioma." (PMID 36186425, 2022). "In multivariate Cox analysis of DSS, high GBP2 expression was an independent prognostic factor for glioma survival." (PMID 36186425, 2022). "Guanylate binding protein 2 (GBP2) is a member of the guanine binding protein family, and its relationship with prognostic outcomes and tumor immune microenvironments in glioma remains elusive." (PMID 36186425, 2022). "This work showed that GBP2 promoted proliferation and migration in glioma cells by regulating EGFR signaling pathway through interactions with KIF22." (PMID 35436989, 2022). "We divided glioma patients into two groups according to GBP2 expression, to analyze the relationship between clinicopathological features and GBP2 expression." (PMID 36186425, 2022). "Kaplan-Meier analysis indicated that high expression of GBP2 was significantly associated with worse overall survival (OS), disease specific survival (DSS) and progress-free interval (PFI) in glioma patients." (PMID 36186425, 2022). "These malignant characteristics in patients with higher GBP2 expression suggested the significant role of GBP2 in gliomas." (PMID 36186425, 2022). "The reliability of GBP2 in predicting the viability of glioma patients was determined by time-dependent ROC curves." (PMID 36186425, 2022). "Single-cell analysis revealed that GBP2 were highly expressed in MES-like glioma subtypes, which showed the high antigen presentation capabilities." (PMID 36186425, 2022). "In glioma cells, depletion of GBP2 impairs proliferation and migration, whereas overexpression of GBP2 enhances proliferation and migration." (PMID 35436989, 2022). "Altogether, these data suggested that GBP2 was significantly correlated with worse prognosis in glioma." (PMID 36186425, 2022). "To further explore the effect of GBP2 expression on tumor immune microenvironment, we examined the malignant cells in glioma patients (GSE131928)." (PMID 36186425, 2022). "By comparing GBP2 expression among different glioma subtypes, we found GBP2 has the highest expression in MES-like cancer cells." (PMID 36186425, 2022). "The GBP2-related ceRNA regulatory network revealed the potential regulatory mechanism of non-coding RNA for GBP2 expression in glioma." (PMID 36186425, 2022).